FCGR1A (Fc gamma receptor Ia)
Diseases named in the same sentence as FCGR1A in open-access papers (continued):
Sharing a sentence is not in itself a finding about the gene and the disease.
periodontitis (4 papers, 2020 to 2025). An acute or chronic inflammatory process that affects the tissues that surround and support the teeth. "Western blot analysis showed an increasing trend in the expression level of FCGR1A protein in the periodontal tissues of experimental periodontitis mice compared to normal mice." (PMID 36212719, 2022). "Western blot analyses showed an increasing trend with the expression level of FCGR1A protein in periodontal tissues of experimental periodontitis mice compared to normal mice; however, the difference was not statistically significant." (PMID 36212719, 2022). "We used the GSE43525 database to verify candidate genes and confirm FCGR1A (CD64) as a key gene in the development of periodontitis." (PMID 36212719, 2022). "FCGR1A (CD64) may be a key gene target for periodontal therapy in patients with periodontitis and other systemic diseases." (PMID 36212719, 2022). "Moreover, FCGR1A exists at the intersection of Venn diagrams; therefore, we speculated that FCGR1A may be a candidate target gene in chronic periodontitis refractory to conventional therapy." (PMID 36212719, 2022).
prostate carcinoma (4 papers, 2001 to 2025). A carcinoma that arises from epithelial cells of the prostate gland. "The high binding affinity between Dt and the FCGR1A, the latter representing one of the principal players in immune cell infiltration, highlights a potential immunomodulatory role of Dt in prostate cancer cells." (PMID 36829917, 2023).
colorectal cancer (3 papers, 2013 to 2025). A primary or metastatic malignant neoplasm that affects the colon or rectum. "Clinical validation of MPO and FCGR1A underscores their potential as biomarkers for early adenoma detection and advanced colorectal cancer monitoring." (PMID 40003985, 2025). "The inclusion of immune-related transcripts, such as MPO and FCGR1A, in the early and advanced stages of colorectal cancer highlights the value of liquid biopsy for cancer detection." (PMID 40003985, 2025). "The identification of circulating biomarkers such as MPO and FCGR1A could contribute to the development of non-invasive screening tools for early colorectal cancer detection, offering potential clinical benefits through more personalized approaches to colorectal cancer management." (PMID 40003985, 2025). "Key transcripts, such as MPO, FCGR1A, DEFA4, and CD177, have been highlighted as potential biomarkers of colorectal cancer, underscoring the role of immune dysregulation in tumor development and progression." (PMID 40003985, 2025).
diabetes (3 papers, 2022 to 2024). "Additionally, other four genes (FCGR1A, NCF2, MYOC, and FABP3) (in bold) were also enriched in these OP- and diabetes-related biological processes and pathways, comparing to the target genes in the TF network." (PMID 36050744, 2022).
idiopathic pulmonary fibrosis (3 papers, 2021 to 2025). Idiopathic pulmonary fibrosis (IPF) is a nonneoplastic pulmonary disease that is characterized by the formation of scar tissue within the lungs in the absence of any known cause. "Using the Idiopathic Pulmonary Fibrosis (IPF) Cell Atlas, we found increased expression of phagocytosis-related genes (FCGR1A, ARPC4, ARPC5) in IPF patients across multiple datasets (available at Rheumatology online)." (PMID 39672802, 2025).
latent infection (3 papers, 2017 to 2021). "FcGR1A is part of the discriminatory gene set in a number of biomarker studies and as a single marker it fairly discriminates active TB from latent infection regardless of HIV status or genetic background." (PMID 29764370, 2018).
malaria (3 papers, 2020 to 2024). Malaria is a serious and sometimes fatal disease caused by a parasite that commonly infects a certain type of mosquito which feeds on humans. "However, consistent with transcriptional upregulation of CD64/FcγRI genes FCGR1A and FCER1G (common FcRγ chain) in children, CD64/FcγRI cell surface expression on monocyte subsets was increased in both children and adults during malaria." (PMID 32566226, 2020). "It has been reported that FCGR1A was upregulated at the protein level on both classical and non-classical monocytes during malaria." (PMID 38360586, 2024).
cervical cancer (2 papers, 2015 to 2020). A primary or metastatic malignant neoplasm involving the cervix. "For example, Bevacizumab and cetuximab has been reported to target FCGR1A and FCGR2B, and these 2 drugs have already been approved for clinical treatment of cervical cancer." (PMID 32733542, 2020).
endocervical carcinoma (2 papers, 2020 to 2022). A carcinoma that arises from epithelial cells of the endocervix. "We also elaborated the important role of FCGR1A in cervical and endocervical cancer (CESC), CHOL, KIRC, and SKCM, as well as revealing a potential relationship among FCGR1A, tumor–immune interactions, and neighboring genes." (PMID 33344503, 2020).
leishmaniasis (2 papers, 2017 to 2023). Infectious disease that is transmitted through the bite of hematophagous female phlebotomine sand flies. "Among these 14 pathways, four major pathways were enriched: SNARE interactions involved in the vesicular transport (BET1 and STX6), leishmaniasis (FCGR1A, CYBB, and FOS), hematopoietic cell lineages (FCGR1A, ITGA3, MME, and CD5) and Fanconi anemia pathway (SLX4, ATR, and TELO2)." (PMID 37601105, 2023).
lung adenocarcinoma (2 papers, 2020 to 2023). A carcinoma that arises from the lung and is characterized by the presence of malignant glandular epithelial cells. "Conversely, FCGR1A had markedly lower expression in lung adenocarcinoma (LUAD), lung squamous cell carcinoma (LUSC), and thymoma (THYM)." (PMID 33344503, 2020).
lymph node metastasis (2 papers, 2020 to 2024). "Higher FCGR1A expression was related to metastasis, higher grade, higher stage, and lymph node metastasis in OC." (PMID 38879666, 2024). "We further analyzed the relationships between FCGR1A and clinical features and found that the expression of FCGR1A was positively correlated with a higher tumor grade and stage and lymph node metastasis." (PMID 38879666, 2024). "Notably, the incidence of lymph node metastasis in the high-FCGR1A group was greater than that in the low-FCGR1A group, which suggests that FCGR1A not only facilitates abdominal metastasis but also may facilitate lymph node metastasis through a certain mechanism." (PMID 38879666, 2024).
osteosarcoma (2 papers, 2021). A usually aggressive malignant bone-forming mesenchymal neoplasm, predominantly affecting adolescents and young adults. "The expression of M1 phenotype markers CD80 and FCGR1A were also downregulated in metastatic osteosarcoma, suggesting that the decreased macrophage M1 might associate with the osteosarcoma metastasis." (PMID 34335756, 2021).
periodontal disease (2 papers, 2022). "As shown in the boxplot, the expression of CD14, FCGR1A, DYNLL1, and FCGR2B correlated with disease status; therefore, these data suggest that these key genes may be important targets for the treatment of periodontal disease." (PMID 36212719, 2022).
adenoma (1 paper, 2025). A neoplasm arising from the epithelium. "This study highlights MPO and FCGR1A as particularly compelling biomarkers for both advanced adenoma detection and early CRC monitoring, addressing key clinical unmet needs in CRC diagnosis and prognosis." (PMID 40003985, 2025). "FCGR1A was significantly upregulated in the advanced adenoma group compared with the HC group, indicating its potential as an early biomarker of adenomas." (PMID 40003985, 2025). "Seventeen DEGs were observed during the transition from non-advanced adenoma to advanced adenoma, with genes such as FCGR1A and S100P showing reduced expression." (PMID 40003985, 2025). "Although upregulated in the non-advanced adenoma group, the FCGR1A difference was not statistically significant." (PMID 40003985, 2025). "An RT-qPCR analysis was performed to validate FCGR1A and MPO levels in 20 samples, each from the advanced adenoma, non-advanced adenoma, and HC groups." (PMID 40003985, 2025).
bovine tuberculosis (1 paper, 2024). "A study with tissue samples of cows with bovine tuberculosis caused by Mycobacterium bovis (Mb) showed the involvement of FCGR1A in the immune response against Mb." (PMID 38668343, 2024).
renal clear cell carcinoma (1 paper, 2022). "FCGR3A (Fc fragment of IgG receptor IIIa) encodes the receptor for the Fc region of immunoglobulin G. FCGR3A interacts with FCGR1A in numerous pathophysiological processes and is substantially related with overall survival (OS) in CM, renal clear cell carcinoma, and other malignancies." (PMID 35957907, 2022).
staphylococcus aureus infection (1 paper, 2020). An infectious process in which the bacteria Staphylococcus aureus is present. "Gene FCGR1A, FCGR3A, and FCGR3B were enriched in both the staphylococcus aureus infection and osteoclast differentiation pathways, and belong to the Fc gamma receptor (FcγR), a receptor for the Fc portion of IgG." (PMID 33344459, 2020).
triple-negative breast carcinoma (1 paper, 2023). An invasive breast carcinoma which is negative for expression of estrogen receptor (ER), progesterone receptor (PR), and human epidermal growth factor receptor 2 (HER2). "FCGR1A is associated with immune infiltration levels in various cancers, and it’s correlated with recurrence-free survival in patients with triple-negative breast cancer (TNBC)." (PMID 36797662, 2023).
infection (162 papers, 2007 to 2026). The state of being infected such as from the introduction of a foreign agent such as serum, vaccine, antigenic substance or organism. "Lm infected 54.45 ± 2.19% wild-type THP-1 cells compared to 44.48 ± 2.98% of FCGR1A-deficient cells representing a statistically significant decrease in infection (p = 0.0095, n = 3)." (PMID 28002492, 2016). "This demonstrated that 62% of the top 50 discriminatory genes from the PBMC challenge overlapped with responses seen in natural infection Twenty of these genes were upregulated, including those involved in immunoglobulin binding (FCGR1A and FCGR1B)." (PMID 39666613, 2024).
tumor (118 papers, 2011 to 2026). "The FCGR1A was moderately or strongly associated with most immune marker genes in DCs, which can induce immune memory responses in cancer and promote anti-tumor immunity." (PMID 33344503, 2020). "Therefore, the association of FCGR1A with diverse immune cell marker genes suggested its role in regulating tumor immunology in CESC, CHOL, KIRC, and SKCM." (PMID 33344503, 2020). "This suggests that FCGR1A promotes tumor invasion by regulating LSP1, making it possible for FCGR1A to promote metastasis by modulating the function of immune cells in the peritoneal microenvironment." (PMID 38879666, 2024). "Survival analysis suggested that the group with higher FCGR1A expression had a lower tumor-free survival rate and a lower overall survival rate than did the group with low FCGR1A expression." (PMID 38879666, 2024). "Three tumor antigens, such as CD247, FCGR1A, and Trap, have been identified in CCA and are associated with a good prognosis and antigen-presenting cell infiltration." (PMID 37138880, 2023). "The elevated expression of CD247, FCGR1A and TRRAP were associated with superior OS and RFS of CHOL, indicating that the three tumor antigens have potential immune-stimulatory effects." (PMID 33685460, 2021). "Based on these results, box plots indicated significant differences in FCGR1A expression levels between the tumor and normal tissues among these four cancer types." (PMID 33344503, 2020). "The correlation between FCGR1A and immune cells or gene marker sets of immune infiltrates was analyzed via Tumor Immune Estimation Resource (TIMER)." (PMID 33344503, 2020). "Differential expression of FCGR1A between tumor and normal tissues and the discrepancies in overall survival (OS) among diverse cancer types were performed by Gene Expression Profiling Interactive Analysis." (PMID 33344503, 2020). "FCGR1A had the strongest correlation with DCs among six tumor-infiltrating immune cells in CESC, KIRC, and SKCM." (PMID 33344503, 2020). "Especially, the candidates ABCA1, MET, and SCD were entangled with tumor metabolism, while FCGR1A and ITGB2 showed the widest interactions with immunological processes." (PMID 32228647, 2020). "Our study provides novel insights into the role of neutrophils in CRC progression, particularly through MPO and FCGR1A, which may serve as critical markers in understanding immune-medicated tumor progression." (PMID 40003985, 2025). "Kaplan–Meier curves revealed that the group with high FCGR1A expression had a lower tumor-free survival rate (hazard ratio of death from OC, HR 1.886, 95% CI 1.395–3.302, p < 0.05) and overall survival rate (HR, 1.776, 95% CI 1.158–3.189, p < 0.05) than did the group with low FCGR1A expression." (PMID 38879666, 2024). "According to the clinical sample microarray data, FCGR1A was positively correlated with higher tumor grade and stage in OC; moreover, the group with high FCGR1A expression had lower tumor-free survival and overall survival rates than the group with low FCGR1A expression." (PMID 38879666, 2024). "Overexpression of LSP1 partially reversed the tumor suppressive effect of FCGR1A downregulation." (PMID 38879666, 2024). "Thus, we can infer that FCGR1A can be regarded as a potential biomarker of cancers and play a role in tumor immunology." (PMID 33344503, 2020). "Besides, Tumor Immune Estimation Resource (TIMER) was utilized to study the correlation between FCGR1A and tumor-infiltrating immune cells." (PMID 33344503, 2020). "And the effect of different FCGR1A expression on four tumor locations varied." (PMID 33344503, 2020). "There was a noticeable correlation between the over expressions of FCGR1A/B/C, FCGR2A, and clinical cancer stages/tumor grade in ccRCC patients." (PMID 35372055, 2022). "Three tumor antigens (CD247, FCGR1A, and TRRAP) correlated with superior prognoses and infiltration of antigen-presenting cells in CHOL were identified using narrow-down analysis, thus promising candidates for mRNA vaccine." (PMID 33685460, 2021).
tumor (continued). "Notably, FCGR1A, CD14, and APOC1 emerged as key features within the model, with APOC1 also serving as a prominent marker for tumor-enriched macrophage subtypes." (PMID 41601657, 2026). "Moreover, FCGR1A expression levels were significantly correlated with the OS of CESC, CHOL, KIRC, and SKCM and had notable differences between tumor and normal tissues in these four cancers." (PMID 33344503, 2020). "Another integrated mRNA–lncRNA signature was developed based on the mRNA species for FCGR1A, RSAD2, CHRDL1, and the lncRNA species for HIF1A-AS2 and AK124454, which may be applied to predict tumor recurrence and the benefit of taxane chemotherapy in TNBC." (PMID 33194705, 2020). "Together, three tumor antigens (CD247, FCGR1A, and TRRAP) were identified as potential candidates for the CHOL-mRNA vaccine with potential immune provocative effects and can be processed and presented by antigen-presenting cells (APCs) to induce a tumor response." (PMID 33685460, 2021). "The results showed that the mRNA levels of FCGR1A/B/C and FCGR3A were correlated with the tumor stages of ccRCC patients, whereas the mRNA levels of FCGR2A/B/C and FCGR3B did not markedly differ among tumor stages." (PMID 35372055, 2022). "Expression level of FCGR1A, although not correlated with VIM or CDH1, had r = 0.31 and r = 0.42 with SNAI1 and SNAI3 respectively, suggesting it may be co-expressed with these EMT drivers in some tumours." (PMID 27876705, 2016).
bacterial infection (65 papers, 2008 to 2026). "At the RNA level, we saw the highest fold-difference in BPI and the lowest fold-difference in FCGR1A (CD64) in progressors compared to non-progressors; both of which are expressed by neutrophils and are important in the control of bacterial infections." (PMID 21966464, 2011).
cancer (56 papers, 2009 to 2026). A tumor composed of atypical neoplastic, often pleomorphic cells that invade other tissues. "Xu confirmed that FCGR3A had highly significant positive associations with FCGR1A in various cancers." (PMID 40660309, 2025). "The level of FCGR1A was positively correlated with inflammation, suggesting that monocyte-associated inflammatory responses were enhanced in patients with cancer during disease progression." (PMID 38735538, 2024). "Our findings also confirmed that FCGR3A had highly significant positive associations with FCGR1A in four cancers." (PMID 33344503, 2020). "All immune cells were significantly associated with FCGR1A expression levels in the four cancers (P < 0.05)." (PMID 33344503, 2020). "The results showed that FCGR1A was significantly associated with prognosis in four cancer types, which were CESC, CHOL, KIRC, and SKCM, respectively." (PMID 33344503, 2020). "This study also indicated that FCGR1A was associated with multiple levels of immune infiltration in cancers." (PMID 33344503, 2020). "FCGR1A has been proposed as a prognostic biomarker in various cancers and may be linked to immune infiltration levels." (PMID 39655195, 2024). "Here, we studied the association between FCGR1A and the prognosis of different cancers." (PMID 33344503, 2020). "Immune phenotype MR analyses revealed CD64 on monocyte (FCGR1A+ monocytes) as the only immune trait causally linked to both PFDN2 and cancer risk." (PMID 41884853, 2026). "The ability of Dt to trigger immunomodulation in cancer cells was previously predicted by the significant binding affinity and pose between Dt and two selected proteins, FCGR1A, and TLR4." (PMID 36829917, 2023). "In this study, we comprehensively analyzed the relationship between the expression of FCGR1A and prognosis of various cancer types using the Gene Expression Profiling Interactive Analysis (GEPIA) database." (PMID 33344503, 2020). "The relationship between FCGR3A and FCGR1A displayed highly significant positive correlation in four cancers." (PMID 33344503, 2020). "To determine the differential expression of FCGR1A in various cancer locations, we used RNA-seq data from TCGA database to explore the relationship between prognosis and FCGR1A expression in multiple cancer types via GEPIA." (PMID 33344503, 2020). "Integration with publicly available single-cell sequencing data revealed that these proteins were mostly macrophage and monocyte-associated with malignant features (TYMP, FCER1G, FCGR1A, SYK, and F13A1), except NNMT, which was highest in cancer-associated fibroblasts (Table EV4)." (PMID 41233595, 2026). "Notably, PTPN1, TRIM46, TRIM17, FCGR1A, IRF5, IRF6, and CAMK2B had a higher frequency of gain mutations in most human cancer types." (PMID 37941546, 2023). "Likewise, cancer grades analysis by TISIDB indicated that mRNA expressions of FCGR1A/B, FCGR2A/B/C, and FCGR3A correlated with cancer grade of ccRCC." (PMID 35372055, 2022). "We explored the expression levels of FCGR1A in 33 cancer types using TCGA data in GEPIA." (PMID 33344503, 2020). "However, relevant between FCGR1A and diverse immune cells varied substantially in different cancer types." (PMID 33344503, 2020). "FCGR1A may be a potential prognostic biomarker and related to immune infiltration levels in diverse cancers, especially in CESC, CHOL, KIRC, and SKCM." (PMID 33344503, 2020). "FCGR1A may play an important role in immune cell infiltration and serve as a prognostic biomarker for four cancers, especially in SKCM." (PMID 33344503, 2020). "Furthermore, significant positive relevance between FCGR1A expression and six immune cells was discovered in four cancers." (PMID 33344503, 2020). "In addition, we sought to investigate the relationship between FCGR1A and some genes that were confirmed to be related to cancers." (PMID 33344503, 2020).